TLR4 (toll like receptor 4)
Diseases named in the same sentence as TLR4 in open-access papers (continued):
Sharing a sentence is not in itself a finding about the gene and the disease.
tumor (continued). "Second, TLR4 activation on immune cells, such as dendritic cells and macrophages, can enhance anti-tumor immune response by promoting the activation and proliferation of T cells." (PMID 37896221, 2023). "During inflammation-to-tumor transition, chronic infection induces TLR4 signaling, which triggers chronic inflammatory microenvironment and promotes cancer progression." (PMID 37576399, 2023). "Tlr4 was correlated with Apc in ApcMin/+Ret+/− female mice (tumor samples: r=0.88, p<0.01; all samples: r=0.73, p<0.005, Pearson correlation) but not in other cohorts." (PMID 39148929, 2023). "Corylin improved intestinal homeostasis to further reduce tumor cell-induced inflammation by inhibiting the TLR4/p38/AP-1 pathway, inflammatory factors, and the contact between bacteria and epithelial cells in CRC mice." (PMID 36845103, 2023). "In this study, the CD3–CD8 tumor–stroma index had a quite pronounced effect on survival among high TLR4 patients." (PMID 36649244, 2023). "Overall, targeting TLR4 in HCC therapeutically has the potential to induce tumor cell death, enhance the anti-tumor immune response, and sensitize tumors to chemotherapy." (PMID 37896221, 2023). "TLR4 is a well-studied receptor that can be expressed by cancer cells, allowing them to avoid detection by the immune system and promoting further tumor growth." (PMID 37701157, 2023). "TLR4 acts as a mediator between innate and adaptive immunity and is expressed in immune cells, epithelial/endothelial cells, and tumor cells." (PMID 37701157, 2023). "GMFG was reported to modulate iron metabolism and TLR4 responses in macrophages which potentially benefit tumor clearance." (PMID 37287069, 2023). "In-depth studies on HCC have shown that the downstream multifunctional NFκB signaling pathway regulated by TLR4 plays a key role in the induction of tumor formation by inflammatory mediators." (PMID 38074679, 2023). "Our research examined the chemotherapeutic activity of arctiin and focused on the TLR4 pathway, which is known to play a crucial role in tumor activation and carcinogenesis." (PMID 37701157, 2023). "With a few notable exceptions, stimulation of TLR1, TLR2 and TLR4 often leads to tumor-promoting effects by inducing immunosuppressive and antiapoptotic signals." (PMID 37112730, 2023). "A separate manuscript from our team is demonstrating that when a TLR4 activator is added to a similar regimen used in this report, then an antibody response can be involved in the anti-tumor rejection response." (PMID 38077403, 2023). "Tumor-derived EVs that contain miR-203 can inhibit DC maturation via the downregulation of the expression of TLR-4 and Tumor Necrosis Factor alpha (TNF-α), impairing the capacity to mediate IL-12-dependent Th1 differentiation." (PMID 37175226, 2023). "This is in line with previous studies which showed that macrophages require TLR4 expression to migrate from the circulation to the tumor microenvironment." (PMID 37223101, 2023). "Positive intratumoral CD3T and CD8T levels, and a high CD3–CD8 tumor–stroma index associated and correlated with a high TLR2 and a high TLR4 immunoexpression." (PMID 36649244, 2023). "Data were extracted from nine studies that reported survival, CRC staging and tumor progression data in relation to TLR4 expression." (PMID 35841426, 2023). "Conversely, the CB2 cannabinoid receptor has been shown to inhibit TLR4 signaling and promote fatty acid oxidation, and pharmacological antagonism of this receptor reduced tumor growth independently of CB2 expression in tumor cells." (PMID 37251409, 2023). "We have previously demonstrated the presence of TLR4 in GBM tumors and the decreased viability of the GBM tumor cell line after lipopolysaccharide (LPS) (TLR4 agonist) stimulation." (PMID 36765551, 2023). "Animal experiments further showed that tumor cells with TLR4 knockdown show a decreased ability to metastasize compared with the control tumor cells after being induced with soluble B7-H3." (PMID 37112730, 2023).
tumor (continued). "Silencing TLR4 using vivo morpholino was performed to elucidate its role in tumor progression in response to ART." (PMID 38144525, 2023). "It has been shown that TLR4 can induce cancer cell proliferation and tumor growth in vivo by coordinating PI3K/AKT signaling pathway." (PMID 37443143, 2023). "Radiotherapy (RT) has been shown to trigger immunogenic cell death with HMGB1 (High Mobility Group Box 1) release by tumor cells and dendritic cells (DCs) activation through TLR4, allowing a tumor antigen-specific T cell immunity." (PMID 37946136, 2023). "We have shown that TLR4 expression decreases with increasing CRC tumor stage at prognosis, and appears to have stage-dependent associations with participant outcomes." (PMID 35841426, 2023). "Collectively, coincident with the results of in vitro experiments, Fn-EVs significantly facilitate tumor growth and metastasis through the TLR4 pathway in BC." (PMID 37221488, 2023). "Typically, tumor cells express Toll-like receptor 4 (TLR4), and the activation of TLR4 signaling pathways results in cytoskeleton modifications, causing T-MPs to shed from cell membrane surfaces." (PMID 37046617, 2023). "NE in NETs can activate TLR-4 on the surface of tumor cells, leading to an accumulation of intracellular PGC1a levels, which enhances the function of mitochondria and accelerates the growth of cancer." (PMID 37188184, 2023). "TLR4, recognized as a pathogen-associated molecular pattern (PAMP), expresses on immune cells and tumor cells." (PMID 36614179, 2023). "TLR4 signaling in macrophages is believed to play a significant role in the pathogenesis of HCC by promoting tumor growth, ΕΜΤ and inflammation." (PMID 37896221, 2023). "Abnormal TLR4 signaling induces cancer cell proliferation, accelerates cancer cell invasion and metastasis, protects cancer cells from apoptosis, and shapes a tumor-favoring cellular microenvironment." (PMID 37576399, 2023). "Inflammatory signals such as toll-like receptor 4 (TLR4) and nuclear factor kappa B (NFκB) promote tumor cell proliferation and migration by producing numerous cytokines and altering matrix, chemotactic growth, and lymphovascular hyperplasia factors." (PMID 38074679, 2023). "It is also verified in patient tissues that TLR4 was significantly lower in the tumor cells than in the normal bone." (PMID 37284323, 2023). "miRNA-122 exerts its tumor suppressive effect by inhibiting cyclin G1, inhibiting the insulin-like growth factor 1 receptor pathway, inhibiting the expression of toll-like receptor 4 in tumor cells, etc.." (PMID 37546394, 2023). "One of the immune mechanisms accounting for both detecting and controlling tumor cell proliferation lies in TLR4-mediated production of inflammatory cytokines in macrophages." (PMID 38139364, 2023). "HMGB1, a substance generated by dying tumor cells, interacts with TLR4, a receptor crucial for both innate and adaptive immune responses, to initiate the processing of tumor antigens by mature DCs and the anticancer immune response." (PMID 37752941, 2023). "S100A11 has been found to be involved in regulating inflammation, cell proliferation, differentiation, and tumor development through binding to Toll-like receptor 4 (TLR4)." (PMID 37510130, 2023). "This is of particular interest in the context of TLR4 research, as PD-L1 has also been shown to block the cytolytic activity of PD-1+ tumor infiltrating CD4+ and CD8+ T cells, which are reliant on dendritic cell -TLR4 interaction." (PMID 35841426, 2023). "In these cells, TLR4 expression has been primarily implicated as a mechanism to manipulate the TIME and achieve increased cell proliferation and tumor expansion." (PMID 36983067, 2023). "Our results showed that IL-6, IL-17, TNF-α, TLR-2 and TLR-4 genes were overexpressed in tumor tissues compared to adjacent normal tissues." (PMID 38075864, 2023).
tumor (continued). "In tumors, C–C motif chemokine receptor-like 2 (CCRL2) enhances TLR4-mediated inflammatory signaling by interacting with membrane TLR4, thereby enhancing anti-tumor T cell responses." (PMID 36658573, 2023). "As MDSCs from TLR4KO mice failed to produce IL-10 and were less effective in reducing macrophage production of IL-12, the TLR4 pathway in MDSCs was considered a promising therapeutic target for promoting anti-tumor immune responses." (PMID 37524886, 2023). "The finding that TLR4 expression decreases with tumor growth is also consistent with the current understanding of tumor development, with tumors often adapting to evade immune detection and control." (PMID 35841426, 2023). "Several authors reported that TLR4 activation promoted the production of immunosuppressive and proangiogenic cytokines by tumor cells, including IL-10, IL-8, TGF-β, and vascular endothelial growth factor." (PMID 36983067, 2023). "The results show that the inhibition of TLR4 activity leads to immune suppression, which limits tumorigenesis and tumor progression in the liver." (PMID 37896221, 2023). "As of now, TLR4 agonists are primarily used as adjuvants in tumor vaccines and in adoptive anti-tumor immunotherapies as well as in dendritic cell-based therapies specific to tumor antigens." (PMID 37588095, 2023). "Despite the biological potential of TLR4 to promote tumor progression, the TLR4-high group had improved overall survival compared with the TLR4-low group." (PMID 37576399, 2023). "Positive TLR4 or PTK2 expression was accompanied by incomplete tumor encapsulation, microvascular invasion, poor differentiation, advanced TNM stage, poor OS, and high recurrence rates in our cohorts." (PMID 37554278, 2023). "ME reversed the expressions of intestinal mucosal barrier markers occluding and ZO-1 in the CAC model by repairing the TLR4 cascade and decreasing inflammatory genes, therefore slowing tumor progression." (PMID 37200915, 2023). "In this study, we screened 19 genes associated with ferroptosis, of which 10 FerDEGs such as TLR4, KRAS and HSF1 were highly expressed and 9 FerDEGs such as MUC1, PROM2 and MT1G were lowly expressed in tumour tissue." (PMID 36936437, 2023). "Tumor antigens can be captured and processed by dendritic cells, which can be stimulated by Lipo-MP-LPS, as described for other TLR4 agonists, leading to the secondary activation of CD4 and CD8 T-cells in periphery." (PMID 37760603, 2023). "There is downregulation of TLR4 expression in tumor tissues in comparison to surrounding or normal tissues." (PMID 38139364, 2023). "While preclinical studies have shown promising results, including reduced tumor growth and improved survival, it is essential to conduct clinical trials to confirm these findings and evaluate the safety and effectiveness of TLR4 antagonists in humans." (PMID 37896221, 2023). "Researchers report that C21 steroidal glycosides can inhibit tumor cells by regulating the Wnt/β-catenin signaling pathway, TLR4/MyD88/NF-κB, AKT signaling pathway, PI3K/AKT/mTOR signaling pathway, and Hippo pathway." (PMID 36985801, 2023). "Since TLR4 is known to be suppressed by CLEC12A, the expression of TLR4 was reduced in tumor tissues and gradually increased with ART treatment." (PMID 38144525, 2023). "In the advanced stages of FIGO, larger tumor sizes, and higher TLR4 expression levels were observed." (PMID 37370894, 2023). "Specifically, molecules released by dead cells due to chemotherapy activate TLR4, which induces tumor inflammation and upregulates survival proteins required for cell growth and tumor invasion." (PMID 36983067, 2023). "HSPs activate tumor cells to produce chemokines through the toll-like receptor (TLR)-4 signaling pathway, which attracts DCs and T lymphocytes." (PMID 37124541, 2023).
tumor (continued). "In fact, TLR4 is a classical inflammation-related signaling pathway common in tumor development, which is closely related to the tumor microenvironment, inflammatory response in the liver, and abnormal differentiation of liver precursor cells." (PMID 37251918, 2023). "Blocking TLR4 with TAK-242 also inhibited the promoting role of AA in tumor growth in AOM/DSS mice and intestine-specific Apc−/− mice." (PMID 37041160, 2023). "TLR-4 activation on macrophages results in production of IL-1 leading to activation of NF-ĸB and activation of T cells responding to tumor cells." (PMID 37514190, 2023). "Mechanistically, neutrophil elastase (NE) released from NETs activated TLR4 on tumor cells, leading to PGC1a upregulation, increased mitochondrial biogenesis, and accelerated tumor cell growth." (PMID 36934105, 2023). "It has been reported that the expression of toll-like receptor 4 (TLR4) is expressed on several kinds of tumor cells and contributes to tumorgenesis, metastasis and development." (PMID 36647071, 2023). "Nevertheless, in the TLR4−/− mice, PepO treatment effectively inhibited tumor growth via preventing TAM from polarizing into M2 tumor-promoting phenotype." (PMID 37925462, 2023). "Intriguingly, Ret expression was significantly correlated with Tlr4 expression in tumor samples from all cohorts of mice (r≥0.79, p<0.04, Pearson correlation) except for the male ApcMin/+Ret+/− mice." (PMID 39148929, 2023). "IFN-γ is stimulated by the activation of TLR4, promoting tumor microenvironment immune surveillance and tumor progression." (PMID 36829917, 2023). "LPS in the cell surface activates TLR-4 signaling pathways, which leads to production of inflammatory cytokines that assist in controlling the tumor cell growth." (PMID 37514190, 2023). "TLR4 was reported to expression in stem cells and cancer stem cells, prompting tumor invasion and migration, which contributes to the poor prognosis of HCC." (PMID 36647071, 2023). "The binding of extracellular HMGB1 to TLR4 inhibits the fusion between phagosomes and lysosomes, which is involved in the cross-presentation of tumor antigens by DCs." (PMID 36949244, 2023). "Treatment with OAd-MSC TLR4−/− also induced increased density of tumor-infiltrating T cells, as well as a lower CD4+/CD8+ ratio." (PMID 36875156, 2023). "Analysis of NSCLC clinical samples and excised normal lung tissue showed an increase in TLR4 expression in tumor samples compared to normal tissue." (PMID 37112730, 2023). "While our findings suggest a likely relationship between TLR4 expression and tumor stage, the relationship between TLR4 and long-term outcome was less clear cut in both our systematic review and genetic analyses." (PMID 35841426, 2023). "Generally speaking, the role of TNC in cancer includes cell proliferation, differentiation or migration, as well as the upregulation of pro-inflammatory and tumor-promoting cytokines due to activation of toll-like receptor-4 (TLR4)." (PMID 37834140, 2023). "It has been observed that TLR4 inhibits tumor cell proliferation and invasion, while also inducing tumor cell apoptosis." (PMID 37781382, 2023). "In the aberrant miR expression, miR-301 is up-regulated in TNBC and promotes tumor growth, cell proliferation, migration, invasion and tamoxifen resistance via the TLR4/NF-kB signaling pathway." (PMID 36834660, 2023). "Another study found intermittent sleep accelerated tumor growth and invasion by recruiting TAMs and activating the TLR4 signaling pathway." (PMID 38105184, 2023). "S. gastrop (P. anaerobius) has been shown to interact with TLR2 and TLR4 on colon cells to regulate a variety of immune cells including MDSCs, TAMs, and granulocyte tumor‐related neutrophils, thus promoting colon carcinogenesis." (PMID 36860568, 2023).
tumor (continued). "Although intratumoral injection of TLR4 agonists has shown promising results, responses outside of the injected tumor sites remained limited, impairing their efficacy and capacity to address hard-to-reach cancers such as OsA." (PMID 37760603, 2023). "The exodus of high mobility group box 1 (HMGB1) late in the course of ICD triggers Toll-like receptor 4 (TLR4)-mediated tumor antigen processing and ultimately drives DC maturation." (PMID 37907944, 2023). "Activating TLR4 on the surface of tumor cells can promote the proliferation and survival of cancer cells, while activating it on immune cells in the tumor microenvironment plays an opposite role." (PMID 37553698, 2023). "The expression of CDK1, ECT2, GJB2, GPR37, GPX2, and GPX8 gene was up-regulated in the tumor group (p < 0.001), whereas the expression of TLR4 was down-regulated in the tumor group (p < 0.001) when compared with those in the normal group." (PMID 37689745, 2023). "Based on the results, the level of ANPEP, HLA‐A, CCL2, TLR4 and SERPINE1 had statistically significant association with tumor purity in UCEC tissues." (PMID 36969077, 2023). "DAMPs activate inflammasomes that are able to coordinate with TLR4 signal to induce IL-1β secretion and adaptive anti-tumor immunity in DCs." (PMID 36932407, 2023). "Consistently, administering a DC vaccine with the TLR4 agonist LPS resulted in a notable increase in NK cells and a significant reduction in Treg cells within the tumor microenvironment in an ovarian cancer mouse model." (PMID 37936697, 2023). "NF‐κB pathway is involved in the regulation of the tumor cell cycle and apoptosis, and TLR‐4 is an upstream molecule for NF‐κB." (PMID 37701204, 2023). "Similar to divalent peptide3A5, divalent ILVIK competitively inhibited S100A8 binding to TLR4/MD-2 and inhibited tumor growth in subcutaneously transplanted SW480 cells in a dose-dependent manner." (PMID 36932197, 2023). "In particular, TLR4 is overexpressed in different metastatic tumor cells positively correlating with tumor cell survival, metastasis, and drug resistance." (PMID 36983067, 2023). "The US-FDA has already approved the use of BCG as an initiator for the TLR4 signaling pathway to generate anti-tumor immune responses against various types of cancers." (PMID 37822929, 2023). "This reduction of inflammation and tumor development was related to an impaired activation of TLR-4-NF-κB signaling cascade in macrophages due to an altered EFTUD2 expression." (PMID 36068443, 2023). "Conversely, the research on pituitary epithelial neoplasms had found that activation of TLR4 impeded tumor cell growth." (PMID 37990304, 2023). "A previous study showed that TLR4 was aberrantly expressed in cancer cells, affecting the tumor microenvironment." (PMID 35754792, 2022). "The association between TLR3, TLR4, and TLR9 expressions and tumor aggressiveness and poor prognosis in HCC was obtained from 30 patients with HCC." (PMID 35434373, 2022). "Together, the results identified tumor-derived redHMGB1 as a priming signal to drive TLR4/mTOR/Bcl6-mediated trained immunity in TAMs." (PMID 36542153, 2022). "According to a previous report, PTX treatment significantly increased pulmonary and lymphatic metastasis incidence and burden by TLR4-positive tumours." (PMID 35280672, 2022). "Previous studies found that in a lung mouse cancer model, this regimen can foster CD8+ T cell infiltration and increase TLR4+ DCs in tumor tissues, and further increase tumor sensitivity to immune checkpoint therapy." (PMID 36619616, 2022). "We found that Eritoran blocked S100A8-mediated TLR4 activation and reduced TAMs and CD11b+Ly6C++Ly6G− populations in tumor microenvironment." (PMID 35780158, 2022). "TLR4 activation induces other tumor-driver genes which cooperatively work with Nanog to initiate liver oncogenesis." (PMID 36187761, 2022).